IL6 (interleukin 6)
Diseases named in the same sentence as IL6 in open-access papers (continued):
Sharing a sentence is not in itself a finding about the gene and the disease.
Arthritis (continued). "This induction was IL-6-dependent in line with the well-established role of IL-6 as a potent inducer of TH17 differentiation, and the major role of IL-6 in the pathophysiology of arthritis." (PMID 28166724, 2017). "In vivo efficacy of the inhibitory effect of PLAG on IL-6 expression was studied in a mouse model of arthritis." (PMID 29228558, 2017). "Secondly, we used IL-6-/- x IL-21R-/- mice to study the in vivo effects of cytokine pathway blockade on Th17 differentiation and development of experimental arthritis." (PMID 28158305, 2017). "The T cell-driven AIA model was induced in WT, IL-6-/-, IL-21R-/-, and IL-6-/- x IL-21R-/- mice, and the number of Th17 cells in draining LNs was assessed two days after arthritis onset." (PMID 28158305, 2017). "The study found that IL-6 has the effect of promoting inflammation, which is closely related to arthritis, tumor and obesity-related diseases." (PMID 29073894, 2017). "In this way, our data clearly indicates that tryptase must be the major mast cell mediator regulating IL-6 production in arthritis." (PMID 28587618, 2017). "We next investigated the in vivo effects of IL-6 and IL-21 pathway blockade on Th17 differentiation and the development of experimental arthritis." (PMID 28158305, 2017). "In mice treated from the day of immunization with anti-IL-6 and anti-IL-21 treatment on the other hand, clinical arthritis severity based on swelling and redness of the four paws was greatly reduced in comparison with the isotype control group." (PMID 28158305, 2017). "We show that the aberrant microbiota in IL1rn−/− mice have the capacity to enhance LP Th17 cells which are associated with arthritis, likely via TLR4-induced production of IL-1β, IL-6, and IL-23." (PMID 28645307, 2017). "The intraperitoneal inoculation also decreased the arthritis incidence, joint damage, and serum level of interleukin (IL)-6." (PMID 28680422, 2017). "This conclusion was based on findings that microinjecting IDO inhibitor directly into rat brain hippocampus abolished pain hypersensitivity, while microinjecting IL-6 stimulated brain IDO expression in this rodent arthritis model." (PMID 27168185, 2016). "Cartilage degradation in arthritis is recognized to be induced by inflammatory cytokines, such as interleukin (IL)-6, IL-1β, and tumor necrosis factor-α (TNF-α)." (PMID 27411719, 2016). "Our study shows that CD146+ cells tended to suppress arthritis progression, as shown by their effects on chondrogenesis, IL-6 and IL-17 cytokine expression, and joint histology." (PMID 26841872, 2016). "They found that co-treatment with anti-TGF-β1, anti-IL-6 and anti-IL-17 antibody reduced the severity of arthritis significantly more than the inhibition of single cytokines in Borellia-vaccinated and challenged mice did." (PMID 27243813, 2016). "We reported recently that mice deficient in TIARP (TIARP−/−) spontaneously develop arthritis and are highly susceptible to collagen-induced arthritis (CIA) with enhanced interleukin (IL)-6 production." (PMID 27995997, 2016). "The importance of IL-6 in CIA has been demonstrated by blocking IL-6, which reduces the severity of arthritis." (PMID 27296719, 2016). "The result is consistent with the previous finding that Sin ameliorates arthritis via suppressing the production of pro-inflammatory cytokines IL1β and IL6 in collagen-induced arthritic rats." (PMID 27869674, 2016). "The induction of arthritis was correlated with a 27-fold increase of serum IL-6 in arthritic ApoE−/− mice compared to arthritic C57BL/6 mice." (PMID 27287704, 2016). "In our study, administration of neovestitol reduced joint damage in animals with arthritis, suggesting therefore its possible influence on the inhibition of IL-6." (PMID 27819273, 2016). "We found that administration of neovestitol reduced the clinical scores of animals with arthritis and the levels of IL-6." (PMID 27819273, 2016).
Arthritis (continued). "SL1026 (1 and 10 mg/kg), administered q.i.d., delayed the progression of arthritis and the concomitant increase in serum IL-6 levels compared to the untreated control group." (PMID 26579954, 2016). "IFN-γ, IL-6, and IL-22 are found to be elevated during the development of arthritis, and inhibition of TNF and IL-6 represents successful treatments of RA." (PMID 28057980, 2016). "While inhibition of IL-6 signaling significantly attenuates murine arthritis, hyperactive gp130 signaling exacerbates inflammation." (PMID 26590032, 2015). "IL-6 is a pleiotropic cytokine that plays role in arthritis but its role in the pathogenesis of AS remains controversial." (PMID 26339141, 2015). "These investigations highlighted the central role of the enhanced signaling mediated through the IL-17A-triggered positive-feedback loop of IL-6 expression in fibroblasts in the development of arthritis in F759 mice." (PMID 26501341, 2015). "We have observed that IL-6 levels increase in the serum of AIA rats throughout the course of arthritis, although abundant production was seen only after 2 weeks of disease onset." (PMID 26658436, 2015). "We found that inhibition of IL-17 during established arthritis caused only a modest decrease in the local expression of MMP3, MMP13 and IL-23, but a marked reduction in systemic IL-6 levels, in accordance with previous reports." (PMID 26081345, 2015). "IL-6 is cytokine with the anti-inflammation and anti-allergy effects that were correlated with arthritis manifestation of SLE30." (PMID 26560501, 2015). "Since a decrease in the number of CD11b+ cells was evident in GPI-immunized Padi4 KO mice, this shortage of IL-6 sources represents one possible explanation for the reduced arthritis severity in Padi4 KO mice." (PMID 26293116, 2015). "In the absence of intra-articular injection of mBSA the levels remain low, whereas if arthritis is triggered by intra-articular injection of mBSA, the serum levels of IL-6, IL-12, IL-17, IFN-γ and TNF increase rapidly again." (PMID 26512984, 2015). "Inhibition of the IL-6 loop significantly suppresses the development of arthritis in F759 mice and in experimental autoimmune encephalomyelitis (EAE)." (PMID 26501341, 2015). "Some studies showed that somatostatin stimulates the production of IL-1β, TNF-α, and/or IL-6 by human blood cells, as well as the expression of IL-1β in articular tissues of rats with ongoing adjuvant-induced arthritis." (PMID 25530957, 2014). "Rats with FCA-induced arthritis had significantly (P<0.01) increased IL-1β, IL-6 and TNF-α expression levels compared with those in the normal control group." (PMID 25289073, 2014). "Because the pattern of effects of IL-1β on sensory neurons of the joint (opposite effects on C- and Aδ-fibers) is different to that of TNF-α and IL-6, it is an intriguing question how neutralization of IL-1β affects pain in arthritis." (PMID 25606597, 2014). "Although the exact molecular mechanisms responsible for cartilage and bone destruction have not been elucidated, studies have shown that pro-inflammatory cytokines TNF-α, IL-1β, and IL-6 play a critical role in the pathological process of arthritis." (PMID 25276195, 2014). "The salient features of three of the key pro-inflammatory cytokines (TNFα, IL-6, and IL-17) involved in arthritis are summarized below." (PMID 25561237, 2014). "Animals were assessed for arthritis symptoms using a clinical score, cytokine levels (human TNFα, IL-1β and IL-6) in sera and joints, and histopathology." (PMID 25344414, 2014). "In the same study, SB203580 also inhibited the circulating concentration of both IL-6 and TNFα in rat and mice with experimentally induced arthritis." (PMID 24995301, 2014). "Chinese propolis also down-regulated IL-6 in Freund's complete adjuvant (FCA) induced arthritis in rats." (PMID 23840273, 2013).
Arthritis (continued). "IL-5 and IL-13 are cytokines related to arthritis suppression, while tissue-destructive cytokines IL-1β and IL-6 induce Th17 cells and promote osteoclastogenesis." (PMID 24456966, 2013). "Microarray analysis of biopsies of inflamed synovium during antigen induced arthritis (AIA) showed an increased M1 signature characterized by upregulation of IL-1β, IL-6 and FcγRI starting from day 1 and lasting up until day 7 after arthritis induction." (PMID 23468840, 2013). "It reduced the severity of arthritis, primarily by reducing cartilage destruction, decreasing IL-6 and TNF-α production and reducing antigen-induced proliferation." (PMID 23349985, 2013). "HLXL-treated rats with AA showed decreased arthritis scores as well as the levels of proinflammatory cytokines (IL-1β, IL-6, IL-17, TNF-α), chemokines (RANTES, MCP-1, MIP-1α, GRO/KC), and MMPs." (PMID 23476694, 2013). "This is supported by evidence indicating that in macrophages PGE2 works in concert with IL-6 to inhibit TNF-α production in a murine arthritis/lupus model." (PMID 24025197, 2013). "A pathogenic factor in the development of arthritis is inflammation driven by proinflammatory cytokines, especially TNF, IL-1β, IL-6, and IL-17." (PMID 24286140, 2013). "In rats with Freund’s complete adjuvant induced arthritis, propolis extracts significantly inhibited the increase of IL-6 in inflammatory tissues." (PMID 23941539, 2013). "Neutralization of visfatin by its inhibitor (APO866) effectively reduced arthritis severity in mice with comparable activity to etanercept, and decreased pro-inflammatory cytokine (IL-1β and IL-6) secretion in affected joints." (PMID 22584415, 2012). "The results demonstrated that IL-17 was the first cytokine to peak (at 12 hours after arthritis induction), followed by IL-6, TNFα, IL-1β, and IFNγ at 24 hours after the challenge." (PMID 22676339, 2012). "Many studies are actually conducted to target IL-17 in arthritis models because of its potential synergistic effects with IL-1β, IL-6, and TNF-α in inducing cytokine expression and joint damage." (PMID 22414623, 2012). "IL-6 blockade inhibits type II collagen-induced arthritis and requires CD4 T cells, which leads to the production of anti-type II collagen IgG." (PMID 23133751, 2012). "We observed induction of IL-1β, IL-6 and IL-17, cytokines already described as key players in the arthritis process and clinically used as therapeutic targets." (PMID 22414623, 2012). "As early as 7 hours after arthritis induction, the amounts of the proinflammatory cytokines IL-1β and IL-6 increased by 12- and 55-fold, respectively, in the SF of sensitized joints." (PMID 22414623, 2012). "In RA, tumor necrosis factor (TNF) primarily contributes to the arthritis effector phase and IL-6 contributes to the arthritis priming phase." (PMID 23133751, 2012). "IL-17 activates synovial fibroblasts and macrophages to stimulate the production of IL-6 and TNFα, which lead to joint inflammation." (PMID 22768242, 2012). "IL-1β, IL-6, and TNFα are elevated in human RA synovium and have also been shown to contribute to the development of arthritis in animal models." (PMID 22414623, 2012). "IL-6 levels in joint tissues were similar in the two groups of mice during antibody-induced arthritis." (PMID 23036692, 2012). "Correspondingly, histological measures of arthritis were reduced, as was tissue expression of IL-6, IL-1β and TNF-α." (PMID 23071771, 2012). "Previous work have shown that IL-6 promotes the development of arthritis as it together with TGF-β induces Th17 cells and stimulates B cells to increased production of IgG and IgA antibodies." (PMID 23166758, 2012). "From these lines of evidence, we propose that TCZ improves anemia in monkey arthritis via the inhibition of IL-6-induced hepcidin production." (PMID 22046525, 2011).
Arthritis (continued). "Furthermore, in IL-6-deficient mice immunized with type II collagen, a decrease of inflammatory cells in knee joints and a reduced antibody response to type II collagen was observed, in agreement with a crucial role played by IL-6 in the development of autoimmune collagen-induced arthritis." (PMID 21682897, 2011). "Other cytokines are also considered to be involved in arthritis, however, and biological medicines targeting them (such as IL-1, IL-6 and IL-17) were developed in different clinical trials." (PMID 21708001, 2011). "Many of the expected cytokines are raised during arthritis in this model, such as IL-1β, IL-10 and IL-6, however, unexpectedly both GM-CSF and TNFα remain low." (PMID 21073728, 2010). "Local treatment with HpTNFR1 markedly reduced mRNA and protein levels of interleukin (IL)-1β and IL-6 in SLC during SCW arthritis and ameliorated CIA." (PMID 20370892, 2010). "Experimental and clinical studies have established prominent roles for TNFα, IL-6 and IL-1 inflammatory pathways in arthritis." (PMID 20497523, 2010). "In murine arthritis models, neutralization of IL-6 transsignalling by administration of sgp130 was shown to reduce inflammation." (PMID 20626857, 2010). "Treatment with neutralizing anti-IL-17 antibodies after the onset of arthritis has also been demonstrated to result in significantly reduced systemic IL-6 levels in wild-type mice." (PMID 19686583, 2009). "Cells other than the G6PI-specific Th cells must therefore produce the pathogenetically relevant IL-6 in G6PI-induced arthritis." (PMID 19640302, 2009). "Prophylactic treatment with anti-IL-6 mAb significantly reduced the incidence and severity of arthritis as compared to control mAb treatment." (PMID 19368720, 2009). "In GPI-induced arthritis, both TNFα and IL-6 antagonists have protective effects, and these cytokines play important roles in the induction of arthritis in collaboration with autoantibodies (anti-GPI antibodies)." (PMID 19660107, 2009). "Studies using IL-6 knockout mice revealed that IL-6 is involved in the severity and progress of experimentally-induced arthritis." (PMID 19228423, 2009). "Matsumoto and coworkers recently found that IL-6 was relevant for the pathogenesis of G6PI-induced arthritis." (PMID 19640302, 2009). "Prophylactic treatment with anti-IL-6 mAb significantly reduced the incidence and severity of arthritis compared to control mAb treated mice." (PMID 19368720, 2009). "Other animal studies have demonstrated that IL-6 is critical in the development of experimental arthritis." (PMID 19368720, 2009). "IL-6 has a pathogenic role in experimental autoimmune models such as EAM, EAE, pristane-induced lupus, experimental-induced arthritis and autoimmune myasthenia gravis." (PMID 19587788, 2009). "Treatment of TNF-driven Tg197 transgenic mice with PIP-18 significantly modulates disease progression by suppressing arthritis indicators (synovitis, cartilage and bone erosion) as well as circulatory levels of murine sPLA2, IL-6, and human TNF-α." (PMID 19765281, 2009). "Like IL-6, IL-8 has been shown to be increased in various inflammatory diseases, including arthritis, that are characterized by elevated mast cells number." (PMID 19133134, 2009). "We also identified that anti-interleukin-6 (IL-6) receptor mAb blocks the development of GPI-induced arthritis." (PMID 19660107, 2009). "The studies reported here were designed to further elucidate the influence of IL-6 in arthritis, by examining the effects of anti-IL-6 mAb treatment in a murine model of type II collagen induced arthritis (CIA)." (PMID 19368720, 2009). "Increased tissue levels of IL-6 in diseases like arthritis, psoriasis, scleroderma, and delayed pressure urticaria have been demonstrated." (PMID 19133134, 2009). "IL-6 is also an important cytokine in arthritis, and it is considered a promising target for the treatment of RA." (PMID 18534002, 2008).
Arthritis (continued). "TNF-α and IL-6 play an important role in GPI-induced arthritis, whereas IFN-γ appears to function as a regulator of arthritis." (PMID 18534002, 2008). "Large amounts of TNF-α and IFN-γ and small amounts of IL-2 and IL-6 were produced by splenocytes from mice with GPI-induced arthritis." (PMID 18534002, 2008). "Among its many functions, IL-6 plays an active role in inflammation, immunology, bone metabolism, reproduction, arthritis, neoplasia, and aging." (PMID 17374166, 2007). "Prolonged exposure to pro-inflammatory cytokines, such as interleukin-1β (IL-1β), tumor necrosis factor-alpha (TNF-α), and interleukin-6 (IL-6) exacerbates inflammation by attracting more immune cells to the affected tissue, worsening conditions such as joint inflammation." (PMID 41242067, 2025). "This might likely be due to IL-6 being primarily secreted by synovial fibroblasts in the synovium of arthritis patients." (PMID 40673198, 2025). "In this model, WT mice developed more severe arthritis compared to IL-6 KO mice." (PMID 40170729, 2025). "Furthermore, in a murine arthritis model, elevated serum IL-6 levels indicate the initiation of local inflammation." (PMID 40918434, 2025). "However, during MSU-induced arthritis, these levels were significantly reduced, indicating that targeting IL-6 can inhibit the activation and phosphorylation of the JAK2-STAT1/3 pathway, thereby alleviating arthritis inflammation." (PMID 40170729, 2025). "Nevertheless, the trend to reduced IL-6 in animals treated with n3-PUFA, the synbiotic, and ldTofa+Syn is in accordance with work from Morin and colleagues, finding a significant reduction in systemic IL-6 in a model of arthritis upon supplementation with purified EPA." (PMID 40491918, 2025). "Decreased expression of RANKL and IL-6, increased number of T cells and the expression of IL-1β in KO mice; IL-17 deficiency did not affect arthritis severity." (PMID 40248692, 2025). "The analysis of this study showed that the effects of triptolide dose, course, and time point varied on various observables: the triptolide course had a significant impact on body weight and arthritis scores, and the triptolide dose dominated many indicators (estrous cycle, IL-6, E2, and FSH)." (PMID 40918529, 2025). "These experiments confirmed that SB alone mimicked key therapeutic effects of EMS, including the amelioration of arthritis, inhibition of pro-inflammatory cytokines (IL-6, TNF-α, and IL-17A), and crucially, the restoration of intestinal barrier integrity (ZO-1 and occludin)." (PMID 41309372, 2025). "Previous research has demonstrated that Guanjietong Pian in conjunction with arthroscopic cleaning for arthritis patients can decrease the amount of interleukin-6 and tumor necrosis factor-α in patients with osteoarthritis of the knee and postpone the need for an artificial joint replacement." (PMID 40295239, 2025). "Similarly, it was demonstrated that 0.5% CLA (c9,t11) reduced arthritis symptoms through the reduction of IL-6 and IL-1β levels in mice comparable to a 1.5 mg/kg dose of celecoxib." (PMID 40806004, 2025). "We discovered that triptolide was successful in lowering IL-6, IL-17A, and arthritis scores." (PMID 40918529, 2025). "TNF inhibitors are effective for steroid-refractory arthritis, while IL-6 inhibitors may be preferred in cases with systemic inflammatory features." (PMID 41239350, 2025). "IL-6 production in SKG mice is indispensable for SKG arthritis development." (PMID 39589811, 2024). "In addition, 50, 100, and 400 mg/kg mangiferin inhibits mRNA expression of cytokine genes in the thymus and spleen of mice with induced-arthritis and lead to decreased serum levels of IL-1β, IL-6, TNF-α, and RANKL by downregulating NF-κB and activating ERK1/2." (PMID 38794160, 2024). "Likewise, interleukin 6 (IL-6) is involved in the pathogenesis and clinical evolution of different diseases such as atherosclerotic vascular disease, arthritis, osteoporosis, sarcopenia, or dynapenia." (PMID 38255091, 2024).